TGFB1 (transforming growth factor beta 1)
Diseases named in the same sentence as TGFB1 in open-access papers (continued):
Sharing a sentence is not in itself a finding about the gene and the disease.
Ewing sarcoma (11 papers, 2011 to 2025). A small round cell tumor that lacks morphologic, immunohistochemical, and electron microscopic evidence of neuroectodermal differentiation. "We also determined the expression of other TGFβ isoforms, TGFB2 and TGFB3, in the immune compartment of Ewing sarcomas and found that TGFB1 is the predominant isoform expressed." (PMID 40858520, 2025). "Here, we demonstrate, using scRNA-seq analysis, that immune cells express TGFB1 in human Ewing tumors." (PMID 40858520, 2025). "We then queried the expression of TGFB1 and found that TGFB1 is most highly expressed by immune cell populations in human Ewing sarcomas, with low expression in tumor and stromal cell populations." (PMID 40858520, 2025). "In the current study, we demonstrate that immune cells are the largest contributors of TGFB1 in the human Ewing sarcoma TME." (PMID 40858520, 2025). "In this study, we use single-cell RNA sequencing analysis of human Ewing tumors to demonstrate that immune cells are the largest contributors of TGFB1 expression in the human Ewing TME." (PMID 40858520, 2025). "We hypothesized that TGFβ1 expression would be increased in tumors developed in an immunocompetent model because our human Ewing sarcoma data demonstrate that TGFB1 is expressed predominantly in the immune compartment." (PMID 40858520, 2025). "Thus, we sought to analyze TGFB1 expression in human Ewing sarcomas on a single-cell level." (PMID 40858520, 2025). "TGFB1 expression is highest in NK cells, CD4+ T regulatory cells, CD8+ T cells, and CD14+CD16− monocytes isolated from human Ewing tumors." (PMID 40858520, 2025). "Taken together, these data demonstrate that Ewing sarcomas developed in an immunocompetent, humanized murine model have increased expression of important modulators of the TME, including TGFβ1, and increased metastatic potential as compared with tumors developed in NSG, immunodeficient models." (PMID 40858520, 2025).
Graves ophthalmopathy (11 papers, 2014 to 2025). An autoimmune disorder of the EYE, occurring in patients with Graves disease. "Transforming growth factor β1 (TGFβ1)-interleukin 11 (IL11) is a newly found critical signaling pathway in fibrotic diseases such as Graves’ orbitopathy (GO)." (PMID 40018034, 2025).
otosclerosis (11 papers, 2013 to 2024). Formation of spongy bone in the labyrinth capsule which can progress toward the stapes (stapedial fixation) or anteriorly toward the cochlea leading to conductive, sensorineural, or mixed hearing loss. "An increase in nonsynonymous variants in the TGFB1 gene was identified in patients with otosclerosis." (PMID 37647735, 2023). "TGFB1 has long been proposed as a susceptibility gene for otosclerosis, but the quality of the supporting evidence has been relatively weak." (PMID 36653343, 2023). "An amino acid variant at position 263 of TGFB1 (I263) was shown to be protective, suggesting that it decreases otosclerosis susceptibility." (PMID 37647735, 2023). "Evidence of an association between rs1800472 in TGFB1 and otosclerosis was found (p = 0.034), this association was strongest amongst non-familial cases (p = 0.011)." (PMID 29728750, 2018). "In summary, our results indicate that down regulation of TGFB1 at transcript and protein level due to de novo mutation −832G > A is associated with otosclerosis development." (PMID 27404893, 2016). "Rare variants in the TGFB1 gene with possible functional significance have been found in otosclerosis cases in some ethnic populations." (PMID 27404893, 2016). "In our previous study, we have identified a de novo heterozygous mutation −832G > A in the promoter of TGFB1 in an otosclerosis patient." (PMID 27404893, 2016). "In this study, we reported the description of a de novo mutation −832G > A in the promoter region of TGFB1 gene inheriting from an otosclerosis patient to her daughter." (PMID 27404893, 2016). "Our findings strengthen the association of TGFB1 (rs1800472) with otosclerosis and support a relationship between RELN and familial otosclerosis only, which may explain previous variable replications." (PMID 29728750, 2018). "Only the association between TGFB1 and otosclerosis was replicated." (PMID 29728750, 2018). "Recently, we have shown the genetic association of −509C > T SNP in TGFB1 gene towards the susceptibility of otosclerosis development and also identified a de novo heterozygous mutation −832G > A in the promoter region of TGFB1 in one patient with otosclerosis." (PMID 27404893, 2016). "In conclusion, this study established the fact that TGFB1 mutation −832G > A altered the TGFB1 promoter activity, which could affect the susceptibility to otosclerosis development." (PMID 27404893, 2016). "Genetic association studies and gene expression analysis of otosclerotic bone showed that the transforming growth factor-beta 1 pathway is an important factor in the pathogenesis of otosclerosis." (PMID 36902548, 2023). "RUNX2 plays a role in bone formation and is also regulated by TGFβ1 and BMP, which have been associated with otosclerosis." (PMID 36498562, 2022). "AHSG can bind both TGFβ1 and BMP, two genes reported to be associated with otosclerosis, and inhibit their activities." (PMID 36498562, 2022). "SSCP analysis of promoter region of TGFB1 identified a de novo 1 base pair (−832G> A) substitution located 1670 bp upstream from the transcription start site (NM_000660.5) in a patient with otosclerosis." (PMID 27404893, 2016). "With the addition of two more genes, the hypothesis rises that the TGFβ1-pathway is involved in the onset of otosclerosis." (PMID 36498562, 2022). "In the two other genes, EYA2 and TGFβ1, no variants were found that were significantly associated with otosclerosis after multiple testing correction." (PMID 36498562, 2022). "Previous studies have shown association between both TGFβ1 and BMP and otosclerosis." (PMID 36498562, 2022). "TGFβ1 has been reported in otosclerosis in previous studies." (PMID 36498562, 2022). "The most recent GWAS was performed as a meta-analysis from three different biobanks: FinnGen, EstBB and UKBB, resulting in the identification of 18 loci associated with otosclerosis, including genes that were previously associated with otosclerosis, e.g., RELN, TGFβ1 and MEPE." (PMID 36498562, 2022).
otosclerosis (continued). "It is possible that decreased TGFB1 expression have impact on these molecules, however, additional studies are needed on this light to understand the complete TGFB1 signaling mechanism in otosclerosis development." (PMID 27404893, 2016). "Further, systemic analysis of TGFB1 gene sequence and expression analysis of this gene might reveal its precise role in the pathogenesis of otosclerosis." (PMID 27404893, 2016). "Here, we genotyped eight previously associated variants in the following six candidate genes: RELN, BMP2, FGF2, COL1A1, TGFB1, and PPP2R5B in a large UK case–control otosclerosis cohort (n = 748)." (PMID 29728750, 2018). "It has been reported that COL1A1, BMP2, BMP4, TGFB1, and RELN genes may also contribute to the development of otosclerosis." (PMID 23864959, 2013).
pituitary tumor (11 papers, 2015 to 2026). A benign or malignant neoplasm affecting the pituitary gland. "It clearly demonstrates that inhibition of MEK/ERK1/2 pathway synergizes with TGFβ1 to inhibit pituitary tumor cell proliferation." (PMID 31231308, 2019). "TGFB1 is an angiogenic growth factor that could show higher levels in pituitary tumors than in normal pituitary tissues." (PMID 37563740, 2023). "Consequently, it would be interesting to explore the role of TGFB1 in PRL pituitary tumor aggressiveness and malignancy." (PMID 26322309, 2015). "However, TGFβ1 produces weak growth inhibitory effect on pituitary tumor cells." (PMID 31231308, 2019). "The expression of PDGFA, PDGFB, TGFB1 and TGFB2 in pituitary tumor tissue was respectively 3.5 x104, 2.0 x 104, 1.3 x 105 and 6.6 x 103 copies/μg total RNA." (PMID 35600354, 2022). "TGFβ1 treatment decreases pituitary tumor cell proliferation, and this inhibitory effect is amplified by MEK inhibitors, because TGFβ1/Smad pathway cross-talks with MEK/ERK1/2 pathway." (PMID 31231308, 2019). "Pituitary tumors also expressed significantly higher levels of angiogenesis growth factors, including VEGFA (4.2-fold), VEGFB (2.2), VEGFC (19.3), PGF (13.4), ANGPT2 (9.2), PDGFA (2.7), PDGFB (10.5) and TGFB1 (3.8) compared to normal pituitary tissue." (PMID 35600354, 2022).
retinal diseases (11 papers, 2017 to 2025). "The roles of angiogenic and proinflammatory factors, including VEGF, TNF, TGFB1, CASP3, IL6, IFNG, and IL1B, and their association with miRNAs and the specified proteins in retinal diseases have been previously reported." (PMID 36180575, 2022).
rhabdomyosarcoma (11 papers, 2012 to 2025). A rare aggressive malignant mesenchymal neoplasm arising from skeletal muscle. "Studies have reported SMAD4 overexpression in Rhabdomyosarcoma cells and suggest that this upregulation is through TGFβ1." (PMID 24688641, 2012). "In rhabdomyosarcoma cells, inhibition and knockdown of G9a reduce the activation of Akt, which is a downstream effector of PI3K; however, the impact of G9a on PI3K/Akt signaling in response to TGFβ1 has not been elucidated." (PMID 40661662, 2025).
vascular malformation (11 papers, 2008 to 2025). A non-neoplastic disorder that is the result of defects of vascular morphogenesis. "This study shows that the Pdgfrβ F7 mutation alone induces vascular malformations by increasing pro-angiogenic gene expression and suppressing TGFβ1 signaling." (PMID 41001557, 2025).
anaplastic thyroid cancer (10 papers, 2019 to 2024). "On the other hand, TGFβ1 was shown to inhibit the growth of the human anaplastic thyroid cancer HTh74, HTh 83, C643 and KAT-4 cell lines." (PMID 36551653, 2022).
androgenetic alopecia (10 papers, 2016 to 2025). "TGFβ1, recognized as a biomarker for hair loss and closely associated with androgenetic alopecia, was significantly down-regulated by our treatment." (PMID 39768251, 2024). "Previous studies have shown that TGFβ1 and 2 of the TGFβ pathway are involved in androgen-induced androgenetic alopecia (AGA) by promoting catagen phase entry." (PMID 32977422, 2020).
chordoma (10 papers, 2015 to 2024). Chordomas are rare malignant tumors arising from embryonic remnants of the notochord in axial skeleton. "In the exophytic chordoma tissues, the expression of tumor cell motility-associated proteins such as TGFβ1, HGDF, THBS2 and FBLN5 were significantly higher than that of the endophytic type." (PMID 25793716, 2015). "To verify the increased expression of FN1 and TGFB1 in recurrent chordoma, we performed IHC analysis in a separate clinical group, which further confirmed their expression levels in recurrent chordoma." (PMID 37784253, 2023). "A more detailed study of TGFβ found that the expression level of TGFB1 was an important factor affecting the prognosis of skull base chordoma, and the down-regulation of TGFB3—a gene that acted opposite to TGFB1—might be a key factor for chordoma tumorigenesis." (PMID 38983929, 2024). "In addition, the well‐known EMT marker TGFB1 has been observed in recurrent chordomas." (PMID 37784253, 2023). "The exact signaling pathway through which TGFβ1 and PTEN play a role in clivus chordoma bone invasion remains to be confirmed by further studies." (PMID 25793716, 2015). "Accordingly, we hypothesized that due to the low level of TGFβ1 expression, the skull base chordoma on one hand promotes inflammation by negative feedback." (PMID 25793716, 2015).
colorectal adenoma (10 papers, 1999 to 2021). An adenoma that arises from the colon or rectum. "Indeed, sulindac treatment has been shown to upregulate apoptosis in certain areas of colorectal adenomas, and these same areas also displayed increased TGFB1 expression." (PMID 24472434, 2014).
corneal dystrophies (10 papers, 2007 to 2026). "Human herpes viruses, TGFβ1-related corneal dystrophies, and the Schnyder corneal dystrophy are great examples of this kind of in vitro studies." (PMID 33525484, 2021).
fungal infection (10 papers, 2008 to 2025). "Recently, we reported that upon fungal infection, monocytes release EVs (MEVCa) containing specific cargo and bearing transforming growth factor beta 1 (TGF-β1) on the vesicle surface." (PMID 35132877, 2021).
metastasis (10 papers, 2013 to 2025). The spread or migration of cancer cells from one part of the body (where they first appeared) to another. "Moreover, we have validated some previously reported overexpressed genes such as TGFB1, IBSP, MMP9, or ITGB3 in bone metastasis; CRYAB, NRCAM, and SOX2 in brain metastasis; VEGF and IL6 in lung metastasis; and CYP4F3 in liver metastasis." (PMID 34051058, 2022).
myeloid neoplasm (10 papers, 2017 to 2024). Proliferation of myeloid cells originating from a primitive stem cell. "In general, TGFB1 expression was negatively correlated with stromal components such as angiogenesis, endothelium, CAFs, matrix, and matrix remodeling, especially in myeloid malignancies." (PMID 37925591, 2023). "For instance, in MSCs derived from the myeloid neoplasms, a remarkable number of genes belonging to the TGF superfamily genes, such as TGFB-1, various BMPs, and INHBA as well as genes of the WNT signaling pathway, were differentially expressed." (PMID 38893194, 2024). "A detailed view into our DESeq2 Data revealed a clear shift to canonical BMP/TGFB-signaling in MSCs from myeloid neoplasms, especially for MDS and AML, reflected by a respective number of genes such as TGFB1, TGFB3L, and a low number of detected genes for MAPK-signaling (via JNK and ERK)." (PMID 38893194, 2024).
Urethral stricture (10 papers, 2014 to 2026). Narrowing of the urethra associated with inflammation or scar tissue. "The transforming growth factor-beta-1 (TGF-β1) is believed to play an important role in the fibrosis underlying urethral stricture as it can directly stimulate fibroblasts to increase the secretion of collagen as well as inhibit the growth of epithelial cells." (PMID 29850566, 2018). "Having observed the activation of canonical Wnt signaling in human urethral fibrosis, we next used a rat model of urethral stricture with local urethral incision and TGFβ1 injection to investigate whether the canonical Wnt signaling is activated." (PMID 37859694, 2023).
biliary atresia (9 papers, 2010 to 2022). A rare, biliary tract disease characterized by progressive obliterative cholangiopathy of the intra- and extrahepatic bile ducts, occurring in the embryonic/ perinatal period, leading to severe and persistent neonatal jaundice and acholic stool. "For example, SPP1, TGFB1, JAG1, STAT1, and VIM were linked to congenital biliary atresia, and were confirmed to be strongly expressed in the endothelial and megakaryocyte." (PMID 34095116, 2021). "E2F regulates cellular proliferation and TGFβ1-induced expression of matrix substrates, while SP1 is a potent inducer of extracellular matrix expression by fibroblasts, but neither has been linked to pathogenesis of biliary atresia." (PMID 20465800, 2010).
bronchiolitis obliterans syndrome (9 papers, 2009 to 2025). A lung disorder that is mainly associated with chronic allograft dysfunction after lung transplantation and that is characterized by inflammation and fibrosis of bronchiolar walls that reduce the diameter of the bronchioles and result in progressive and irreversible airflow obstruction. "Gene expression profiling of human and murine organizing pneumonia lesions showed in part comparable expression levels of pivotal genes, notably of TGFB1/Tgfb1, TIMP1/Timp1, TIMP2/Timp2, COL3A1/Col3a1, CXCL12/Cxcl12, MMP2/Mmp2 and IL6/Il6." (PMID 27282780, 2016).
endometrial tumors (9 papers, 2009 to 2023). "Our mouse endometrial tumors showed an inverse enrichment of TGFB1 target signature molecules as compared to the human endometrial epithelial cell cultures." (PMID 32483112, 2020).
Hashimoto thyroiditis (9 papers, 2012 to 2025). An autoimmune disorder caused by the production of autoantibodies against thyroid tissue. "It is to be emphasized that high expression levels of TGFB1 and of COL1A1 genes in chronic thyroiditis and its correlation with thyroid fibrosis has previously been observed." (PMID 22397327, 2012).
Hodgkins lymphoma (9 papers, 2011 to 2022). A heterogeneous group of malignant lymphoid neoplasms of B-cell origin characterized histologically by the presence of Hodgkin and Reed-Sternberg (HRS) cells in the vast majority of cases. "In the group of patients presenting a nodular sclerosis subtype, the immune profile switched at relapse, with an upregulation of LGALS1 and TGFB1 and downregulation of CD163, CD274, HGF, IL15, and ICOS." (PMID 36230815, 2022).
postmenopausal osteoporosis (9 papers, 2019 to 2025). Metabolic disorder associated with fractures of the femoral neck, vertebrae, and distal forearm. "The direct interactions of rutin, beta-sitosterol, quercetin, norisoboldine, and hyperoside with key disease-related proteins such as TGFB1, TNF, IL1B, IL6, and CAT suggested that these compounds may modulate critical pathways involved in the pathology of postmenopausal osteoporosis." (PMID 39596387, 2024).
Pruritus (9 papers, 2011 to 2026). Pruritus is an itch or a sensation that makes a person want to scratch. "Similarly, a positive correlation with pruritus NRS was observed for IL4R, CXCR1, TGFB1, IL13RA2." (PMID 41268562, 2025).
acute lung injury (8 papers, 2014 to 2025). A condition of lung damage that is characterized by bilateral pulmonary infiltrates (pulmonary edema) rich in neutrophils, and in the absence of clinical heart failure. "TGFβ1 blocks endotoxin-induced hypotension and improves survival in rat models, it decreases the number of neutrophils during the onset of LPS-induced acute lung injury and promotes the release of IL-6 from mast cells, which promotes neutrophil clearance." (PMID 37875957, 2023).
cerebral infarction (8 papers, 2021 to 2025). An ischemic condition of the brain, producing a persistent focal neurological deficit in the area of distribution of the cerebral arteries. "Previous studies suggest that polymorphisms and haplotypes in the TGFβ1 gene are associated with cerebral infarction and ICH." (PMID 34484198, 2021).
E. coli infection (8 papers, 2020 to 2024). "This study demonstrated that the TGFβ1-HH cascade repressed BMECs’ immune reaction upon E. coli infection." (PMID 38360663, 2024). "We therefore presumed that such TGFβ1-mediated intercellular communication between astrocytes and endothelium was largely disturbed during meningitic E. coli infection." (PMID 34281571, 2021). "However, whether such TGFβ1-mediated intercellular cross-talking within BBB could be hijacked during meningitic E. coli infection is entirely unknown." (PMID 34281571, 2021). "In this work, we showed that exogenous TGFβ1 and induced noncanonical Hedgehog (HH) signaling suppressed the endothelial immune response to meningitic E. coli infection via upregulation of intracellular miR-155." (PMID 38360663, 2024).
intracerebral hemorrhage (8 papers, 2018 to 2023). A cerebrovascular disorder characterized by bleeding into one or both cerebral hemispheres including the basal ganglia and the cerebral cortex. "In this sense, it has been reported that endothelial progenitor cells improved the neurological function of rats with intracerebral hemorrhage by decreasing pro-inflammatory cytokines such as IFN-γ, IL-6, and TNFα, and increasing anti-inflammatory cytokines such as TGFβ1 and IL-10." (PMID 29720269, 2018). "Interestingly, treating with TGFβ-1 did not increase CCL2 gene expression and led to improved function in a microglia-mediated inflammation study of intracerebral hemorrhage." (PMID 31829243, 2019).